PJA2 (praja ring finger ubiquitin ligase 2)
Description:
Has E2-dependent E3 ubiquitin-protein ligase activity. Responsible for ubiquitination of cAMP-dependent protein kinase type I and type II-alpha/beta regulatory subunits and for targeting them for proteasomal degradation. Essential for PKA-mediated long-term memory processes. Through the ubiquitination of MFHAS1, positively regulates the TLR2 signaling pathway that leads to the activation of the downstream p38 and JNK MAP kinases and promotes the polarization of macrophages toward the pro-inflammatory M1 phenotype. Plays a role in ciliogenesis by ubiquitinating OFD1.
Synonyms: Praja2; KIAA0438; RNF131; Neurodap1
Tractability: Antibody: UniProt places it where antibodies can reach, with high confidence; its Gene Ontology location is reachable by antibodies, with high confidence. PROTAC: ubiquitination databases record sites on it.
Gene: Protein-coding gene on chromosome 5 (109,334,704 to 109,409,991, reverse strand). Ensembl gene ENSG00000198961.
Subcellular location: Cytoplasm; Cell membrane; Endoplasmic reticulum membrane; Golgi apparatus membrane; Synapse; Postsynaptic density; Cytoplasm, cytoskeleton, microtubule organizing center, centrosome
Subcellular location (Human Protein Atlas): Basal body; Cytosol; Microtubules; Primary cilium; Primary cilium transition zone
Pathways (Reactome):
Immune System: Antigen processing: Ubiquitination & Proteasome degradation
Gene Ontology:
Molecular function: cAMP-dependent protein kinase inhibitor activity; protein binding; ubiquitin protein ligase activity; ubiquitin-protein transferase activity
Biological process: inflammatory response; innate immune response; positive regulation of cAMP/PKA signal transduction; positive regulation of JNK cascade; positive regulation of p38MAPK cascade; positive regulation of toll-like receptor 2 signaling pathway; proteasome-mediated ubiquitin-dependent protein catabolic process; protein ubiquitination; regulation of macrophage activation; long-term memory
Cellular component: centriolar satellite; centrosome; cytoplasm; cytosol; endoplasmic reticulum membrane; Golgi membrane; plasma membrane; ciliary basal body; postsynaptic density; synapse; glutamatergic synapse
Genetic constraint (gnomAD): Loss-of-function variants: 20 observed, 60.54 expected, observed/expected ratio (o/e) 0.33, 90% interval 0.23 to 0.48. The upper end of that interval is the gene's LOEUF score, 0.48, which puts it in group 2 of 6, group 1 being the genes least tolerant of losing a copy. Missense variants: 764 observed, 812.25 expected, observed/expected ratio (o/e) 0.94, 90% interval 0.89 to 1. Synonymous variants: 284 observed, 273.75 expected, observed/expected ratio (o/e) 1.04, 90% interval 0.94 to 1.14.
Homologues: Orthologues: chimpanzee PJA2 (99% identical), macaque PJA2 (97% identical), pig PJA2 (89% identical), rabbit PJA2 (88% identical), dog PJA2 (88% identical), mouse Pja2 (83% identical), guinea pig PJA2 (82% identical), rat Pja2 (82% identical), tropical clawed frog pja2 (43% identical), zebrafish pja2 (33% identical). Paralogues in human: PJA1 (40% identical).
Diseases named in the same sentence as PJA2 in open-access papers:
PJA2 is named in the same sentence as 37 diseases in open-access papers, as found by Europe PMC text mining. Sharing a sentence is not in itself a finding about the gene and the disease. The quoted sentences say what the papers report.
gastric cancer (6 papers, 2021 to 2025). A primary or metastatic malignant neoplasm involving the stomach. "For example, single‐cell sequencing datasets for gastric cancer (HRA001689) reveal expression trends of the PJA2/HDAC2 axis that parallel those observed in colorectal cancer datasets (HRA000201)." (PMID 39928532, 2025). "We also found that the PJA2 gene is often found in oncogene sequences of non‐small cell lung cancer, gastric cancer, lung cancer, glioblastoma, thyroid carcinoma, and so on." (PMID 34541834, 2022). "We tried to elaborate the molecular mechanism of ETS-like transcription factor 4 (ELK4) affecting gastric cancer (GC) progression through M2 polarization of macrophages mediated by lysine-specific demethylase 5A (KDM5A)-Praja2 (PJA2)-kinase suppressor of ras 1 (KSR1) axis." (PMID 34372882, 2021). "In gastric cancer cells and tumor associated macrophages, ELK4 might possibly activate lysine-specific demethylase 5A (KDM5A), which inhibits the expression of Praja 2 (PJA2), thus decreasing kinase suppressor of Ras 1 (KSR1)." (PMID 37381723, 2023). "In gastric cancer, ELK4 plays a role in regulating the lysine-specific demethylase 5 (KDM5A)/Praja-2 (PJA2)/kinase suppressor of RAS1 (KSR1) axis." (PMID 37381723, 2023).
glioblastoma (5 papers, 2016 to 2025). The most malignant astrocytic tumor (WHO grade IV). "A recent study found that PJA2 induces ubiquitin/proteasomal degradation of Mob1 (Mps one binder 1), a kinase regulator of the Hippo cascade, promoting glioblastoma formation." (PMID 28966725, 2017). "Gene RAB3GAP2 (RAB3 GTPase activating non-catalytic protein subunit 2) was implicated in neurodevelopment and Warburg Micro syndrome, whereas PJA2 (praja ring finger ubiquitin ligase 2) degraded MOB1 to support glioblastoma growth." (PMID 27100869, 2016).
glioma (3 papers, 2017 to 2022). A benign or malignant brain and spinal cord tumor that arises from glial cells (astrocytes, oligodendrocytes, ependymal cells). "In a TCGA study with merged cohort of Low Grade Glioma (LGG) and GBM, PJA1, PJA2 Smad3 and altered in 9%, 4% and 14% of samples, respectively." (PMID 28966725, 2017).
atherosclerosis (2 papers, 2022). A disease characterized by the build-up of fatty material and calcium deposition in the arterial wall resulting in partial or complete occlusion of the arterial lumen. "One study demonstrated the association of PJA2 with atherosclerosis through protein–protein interaction network analysis." (PMID 36539828, 2022). "Several risk markers related to the immune response that have key roles in atherosclerosis were identified, including the top aging marker MMP8, disease markers KIR3DL1 and MAGEA6, network markers based on degree (RBM10, PJA2, and CMTM6), and network markers based on betweenness (IRAK1 and VAMP8)." (PMID 35706446, 2022).
colorectal cancer (2 papers, 2022 to 2025). A primary or metastatic malignant neoplasm that affects the colon or rectum. "Secondly, we have focused on exploring the role and potential mechanisms of the PJA2/HDAC2 axis in colorectal cancer cells, but we recognize that further investigation into its effects in other tumor types is warranted." (PMID 39928532, 2025). "Nevertheless, the role of PJA2 as an E3 ubiquitin‐protein ligase in colorectal cancer (CRC) progression remains unexplored." (PMID 39928532, 2025). "Using qRT‐PCR, we detected the expression levels of PJA2 and TRIM36 mRNA in 20 pairs of colorectal cancer tissue samples from our center and found that the expression of PJA2 in colorectal cancer tissues was more significantly different." (PMID 39928532, 2025). "Therefore, we focused on the role of the ubiquitin ligase PJA2 in the development of colorectal cancer." (PMID 39928532, 2025). "PJA2, an E3 ubiquitin‐protein ligase, actively restrains colorectal cancer (CRC) progression." (PMID 39928532, 2025). "Besides, the H&E staining results also indicated that PJA2 could restrain the proliferation and progression of colorectal cancer." (PMID 39928532, 2025). "To better identify the expression level of PJA2 in CRC, we detected the mRNA and protein levels of PJA2 in samples from colorectal cancer patients: 100 samples for qPCR (CRC cohort), 18 cases for WB, and 50 samples for IHC (TMA cohort)." (PMID 39928532, 2025).
brain cancer (1 paper, 2017). A primary or metastatic malignant neoplasm affecting the brain. "Interestingly, although we observed PJA2 mutations in brain cancer, we found no mutations in PJA1, only alterations leading to raised PJA1 expression." (PMID 28966725, 2017).
breast carcinoma (1 paper, 2024). "Using an engineered metastatic niche, we identified a 9‐gene signature (Dhx9, Dusp12, Fhl1, Ifitm1, Ndufs1, Pja2, Slc1a3, Soga1, Spon2) that successfully delineated metastatic breast cancer from nonmetastatic breast cancers including an invasive cell line without metastatic potential." (PMID 38193115, 2024).
colorectal adenocarcinoma (1 paper, 2025). The most common type of colorectal carcinoma. "Among these genes, the expression of the IFIT family was remarkably upregulated in the OE‐PJA2 group, which was also verified by the positive correlation between mRNA levels of PJA2 and the IFIT family in colorectal adenocarcinoma at the Chipbase database." (PMID 39928532, 2025).
Insulin resistance (1 paper, 2021). Increased resistance towards insulin, that is, diminished effectiveness of insulin in reducing blood glucose levels. "SIK2 phosphorylates p35 priming for the ubiquitin ligase PJA2, which is followed by its proteasome-mediated degradation, which leads to insulin resistance (IR), which results from chronic insulin exposure." (PMID 33923622, 2021).
pancreatic cancers (1 paper, 2022). "Suppression of PJA2 expression enhances Wnt signaling; thus promoting proliferation and invasion in pancreatic cancer cells." (PMID 35409166, 2022).
Sepsis (1 paper, 2021). Sepsis is defined as life-threatening organ dysfunction caused by a dysregulated host response to infection. "Another study revealed that PJA2 contributed to MFHAS1 ubiquitylation, positively regulating TLR2-mediated JNK/p38 pathway, which stimulated M1 macrophage polarization as well as M2 to M1 macrophage transformation in sepsis." (PMID 34372882, 2021).
tauopathy (1 paper, 2025). Neurodegenerative disorders involving deposition of abnormal tau protein isoforms (tau proteins) in neurons and glial cells in the brain. "Whether and how HERC1, PJA2, and MYCBP2 participate in tauopathy and mediate the protective effect of sorafenib requires further scrutiny." (PMID 41311387, 2025).
viral infection (1 paper, 2017). "More specifically, PJA2 is well expressed in CD4+ Jurkat and Sup-T1 T cells, highlighting that this ubiquitin ligase can regulate Tat activity during natural viral infection." (PMID 28345603, 2017).
cancer (14 papers, 2016 to 2025). A tumor composed of atypical neoplastic, often pleomorphic cells that invade other tissues. "Of note, the translation enhancing uORF variant in PJA2 occurred in four of six tumor entities investigated here, hinting towards a potentially widespread functional impact in human cancer." (PMID 34072580, 2021). "In the future, further validations could test cancer cell activity after silencing LGAT93.1 to assess the variations in the expression levels of the associated gene PJA2, which could help to reveal the underlying role of LGAT93.1 in LGG." (PMID 31877126, 2019). "The nine genes identified in our signature (Dhx9, Dusp12, Fhl1, Ifitm1, Ndufs1, Pja2, Slc1a3, Soga1, and Spon2) have each been investigated for their role in cancer." (PMID 38193115, 2024). "In contrast, Pja2 (Praja Ring Finger Ubiquitin Ligase 2; UniProt O43164) promotes anti‐cancer M1 macrophage polarization." (PMID 38193115, 2024). "Praja2 (PJA2), belonging to the growing family of mammalian RING E3 ubiquitin ligases, has been found to be implicated in different cancers and neurological diseases." (PMID 34372882, 2021). "We further analyzed genetic alterations of PJA1 and PJA2 that include copy number (CPN) gain, amplification, shallow deletion, deep deletion and mutations in 36 different cancer types." (PMID 28966725, 2017). "It was found that PJA2 is able to ubiquitylate KSR1 to regulate the growth of cancer cells." (PMID 34372882, 2021). "Notably, downregulated PJA2 shared correlation with worse overall survival of patients with GC and PJA2 was thus suggested as a potential plasma circRNA biomarker for this cancer type." (PMID 34372882, 2021). "Given the importance of HDACs and E3 ligases in cancer biology, the proposed feedback loop involving HDAC2 and PJA2 may represent a common regulatory mechanism in other cancers." (PMID 39928532, 2025). "All patients with cases of PJA2 overexpression survived without cancer recurrence during the follow-up period, although the differences for disease-free (p = 0.153) or overall survival (p = 0.272) were not significant." (PMID 30651076, 2019). "Thus, PJA2 emerges as a multifaceted target, with implications not only for direct tumor suppression but also for modulating the tumor's interaction with the host's immune system, offering a promising avenue for the development of personalized and combinatorial cancer treatments." (PMID 39928532, 2025).
tumor (13 papers, 2016 to 2025). "With the overexpression of PJA2, the inhibition of tumor growth caused by interferon could be amplified, and the depletion of PJA2 caused contrary phenomena." (PMID 39928532, 2025). "Results showed that cells with depleted PJA2 promoted tumor proliferation, as evidenced by greater tumor weight and volume." (PMID 39928532, 2025). "Given that tumor proliferation is the most classical feature of the malignant phenotype, the role of PJA2 in CRC proliferation was explored." (PMID 39928532, 2025). "In this context, PJA2 is recognized as a tumor suppressor that can inhibit tumor proliferation and promote apoptosis by restraining HDAC2‐related transcription of the IFIT family." (PMID 39928532, 2025). "In CRC tissues, the upregulated HDAC2 due to the reduction of PJA2 restrains the transcription of PJA2 and forms a feedback loop to aggravate tumor progression." (PMID 39928532, 2025). "Collectively, these results suggest that PJA2 functions as a tumor suppressor by inhibiting proliferation and promoting apoptosis in CRC." (PMID 39928532, 2025). "The downregulated HDAC2, in turn, restrains the transcription of PJA2, forming a feedback loop that enhances the tumor‐inhibitory effect of PJA2." (PMID 39928532, 2025). "Compared to the control group, the knockdown of PJA2 restrained the tumor suppression effect of interferon, as evidenced by larger tumor weight and volume, elevated Ki‐67 staining, and decreased Tunel staining." (PMID 39928532, 2025). "And we also analyzed the TCGA data and found that the mRNA expression levels of UCHL1 and PJA2 in tumor are lower than those in normal tissue, consistent with their protein expressions." (PMID 38918720, 2024). "Taken together, PJA2 acted as a tumor suppressor to regulate PC malignant behaviors via the FTO–PJA2–Wnt axis in an m6A-YTHDF2-dependent way, indicating that PJA2 is a new promising molecular target for PC therapeutic treatment." (PMID 35936737, 2022). "Emerging evidence has shown that PJA2 was aberrantly expressed across cancers and acts as an oncogene or a tumor suppressor in thyroid cancer, glioblastoma, and gastric cancer." (PMID 35936737, 2022). "First, while our study primarily verifies that PJA2 can regulate tumor proliferation and apoptosis, the role of PJA2 in other malignant phenotypes such as invasion and migration remains unknown." (PMID 39928532, 2025). "Moreover, HDAC2‐wt restored tumor proliferation suppressed by PJA2, and HDAC2‐mut promoted tumor growth and inhibited tumor apoptosis compared with HDAC2‐wt in PJA2 overexpressed cells." (PMID 39928532, 2025). "We found that both mRNA and protein levels of PJA2 were downregulated in tumor tissues." (PMID 39928532, 2025). "Consistently, the overexpression of PJA2 amplified the tumor suppression function of interferon." (PMID 39928532, 2025). "All these findings demonstrate that PJA2 interacts with HDAC2 to promote the polyubiquitination and degradation of HDAC2, eliminating the transcriptional inhibition of the IFIT family and PJA2 caused by HDAC2, forming a positive feedback loop and inhibiting tumor proliferation." (PMID 39928532, 2025). "Our present study suggests the CD1d- and PJA2-related tumour microenvironment might be crucial for IMPC." (PMID 30651076, 2019). "Thus, we speculate that PJA2 overexpression in vivo may contribute to tumor progression by affecting MFHAS1 expression and function." (PMID 34072580, 2021). "In IMPC, M2 macrophage polarization by a shortage of PJA2 might facilitate tumour progression." (PMID 30651076, 2019). "The CD1d- and PJA2-related tumour microenvironment might be crucial for IMPC." (PMID 30651076, 2019). "Xenograft tumor models showed that the group with HDAC2 knockdown or treatment with Romidepsin suppressed tumor weight and volume compared with tumors with PJA2 knockdown alone." (PMID 39928532, 2025).
tumor (continued). "Collectively, these data indicated that PJA2 promotes the transcription of the IFIT family and amplifies the anti‐tumor effect of interferon." (PMID 39928532, 2025). "In this investigation, to explore a potential role for PRAJA in tumorigenesis, we conducted a genomic analysis of Praja1 (PJA1), Praja2 (PJA2) and Smad3 across 29 tumor types." (PMID 28966725, 2017). "Conversely, the overexpression of PJA2 in HCT116 and DLD‐1 suppressed tumor cell proliferation." (PMID 39928532, 2025).
PJA2 also shares sentences with these, for which no sentence is quoted: Alzheimer disease (2 papers); neurological diseases (2); thyroid cancer (2); astrocytoma (1); autism spectrum disorder (1); brain tumor (1); chronic kidney disease (1); clear cell renal cell carcinoma (1); colon cancer (1); endocrine cancers (1); invasive breast carcinoma (1); kidney cancer (1); kidney tumors (1); lung adenocarcinoma (1); lung carcinoma (1); lymph node metastasis (1); medulloblastoma (1); neuroblastoma (1); non‐small cell lung cancer (1); oligoastrocytoma (1); prostate carcinoma (1); Warburg micro syndrome (1).